IL6 (interleukin 6)
Diseases named in the same sentence as IL6 in open-access papers (continued):
Sharing a sentence is not in itself a finding about the gene and the disease.
Alzheimer disease (continued). "Alzheimer’s disease is also closely associated with low-grade chronic inflammation as highlighted by a number of increased systemic inflammation markers including C-reactive protein (CRP), fibrinogen, interleukin-6 (IL-6), and tumor necrosis factor α (TNF-α)." (PMID 25225492, 2014). "For example, elevated levels of IL-6 occur in the CNS or CSF of patients with clinical depression, active epilepsy, Alzheimer’s disease, HIV infection and inflammatory neurological disorders." (PMID 25177271, 2014). "Pro-inflammatory stimuli, including cytokines like Interleukin-1β, Interleukin-6 and Interferon-γ, in the brain have been proposed to exacerbate existing Alzheimer’s disease (AD) neuropathology by increasing amyloidogenic processing of APP and promoting further Aβ accumulation in AD." (PMID 22838967, 2012). "Thus, inhibition of pathological IL-6 expression provides a rationale strategy for targeting the onset or further progression of neurological disorders including Alzheimer's disease, multiple sclerosis, Parkinson's disease and traumatic brain injury." (PMID 21801384, 2011). "For example, elevated levels of pro-inflammatory cytokines such as interleukin-6 (IL-6) and tumor necrosis factor-α (TNF-α), commonly linked to gut dysbiosis in Alzheimer’s disease, have also been reported in ALS patients and may accelerate disease progression." (PMID 41184709, 2025). "Pentameric C-reactive protein (CRP/hsCRP) and its counterpart interleukin-6 (IL-6 are key acute-phase reactants recognized as biomarkers and potential mediators at the interface between systemic autoimmune inflammation and neurodegenerative disease, particularly Alzheimer’s disease (AD)." (PMID 41373439, 2025). "Interestingly, IL-6 appears to be associated with an increased risk of developing all-cause dementia, but this marker is not specific to Alzheimer’s disease." (PMID 39201378, 2024). "However, intermittent systemic sgp130-Fc dosing reversed CCI-induced increases in IL-6 sensitive chemokines MIG, IP-10, and MIP-1β, which are known to perpetuate neuroinflammation in other neurological diseases like encephalitis, MS, and Alzheimer’s disease, where IL-6 signaling also plays a role." (PMID 38840141, 2024). "Consequently, dysregulation of IL-6 emerges as a substantial factor in various neurological disorders, including Alzheimer’s disease (AD), Parkinson’s disease (PD), and Huntington’s disease (HD), Multiple Sclerosis (MS), Amyotrophic Lateral Sclerosis (ALS) an others." (PMID 39015561, 2024). "In Alzheimer’s disease, β-amyloid plaques are surrounded by reactive glial cells (microglia and astrocytes) showing elevated expression of proinflammatory factors such as IL-1β, IL-6, TNF-α, and nitric oxide, while anti-inflammatory cytokines (TGF-β1 and IL-10) are at reduced levels." (PMID 36298702, 2022). "Indeed, an increase in the IL-6 levels is seen in several neurological conditions, such as Alzheimer’s disease (AD), Parkinson’s disease, and Multiple Sclerosis, and elevated plasma levels of IL-6 increase the risk of developing dementia and precedes the onset of AD." (PMID 35163295, 2022). "Moreover, earlier, Fedorova and co-authors showed that marinobufagenin treatment of mice with Alzheimer’s disease (AD) significantly decreased the inflammatory marker interleukin-6 (IL-6) mRNA in the cortex, which was higher in the AD mice than in wild-type mice." (PMID 34948068, 2021). "However, from an anti-inflammatory point of view, this reduction of both IL-1β and IL-6 could explain the hypothesis, proposed by Borokivova46, according to which ACh levels decrease can favor neuroinflammatory events, as observed in Alzheimer disease." (PMID 31578381, 2019). "In the elderly, an increased production of proinflammatory cytokines such as IL-6 was observed, which proves the link between tumorigenesis and the aging process; miR-21 was also found elevated in other ARDs such as hypertrophic heart, neointimal formation and Alzheimer’s disease." (PMID 26697428, 2015).
Alzheimer disease (continued). "Several studies have shown an association with cognitive decline and IL-6 but most studies observed an association with vascular dementia but not Alzheimer’s dementia, suggesting that underlying CV conditions could be responsible for such association." (PMID 24244750, 2013). "Both IL-6 and TNF-α are neurotoxic and are elevated in other neurodegenerative conditions including Alzheimer’s disease." (PMID 41009444, 2025). "JWX-A0108 improved the learning and memory function of Alzheimer’s disease model APP/PS1 mice by decreasing the expression of TNFalpha, IL-1beta, and IL-6 and also decreasing the phosphorylation of NF-kappaB." (PMID 37994990, 2024). "EA reduces the expression of IL-1β, IL-6, and TNF-α in the hippocampus of mice with Alzheimer’s disease and acute myocardial ischemia, exerting an anti-inflammatory effect." (PMID 38629101, 2024). "Studies of Alzheimer’s disease show inflammatory cytokines such as TNF-α, IL-1, IL-6, and IL-8 are released from the host cells that have been infected with Porphyromonas." (PMID 37007475, 2023). "Several SASP factors, including IL-6, IL-1β, TNF-α, MMP-1, MMP-3, and MMP-10, have also been found to be elevated in the cerebrospinal fluid and serum of patients with Alzheimer’s disease." (PMID 37569663, 2023). "The combined application of ALC+quercetin in an animal model of Alzheimer's disease also significantly reduced hippocampus levels of inflammatory biomarkers, like TNF-α and IL-6." (PMID 35936217, 2022). "BBB disruption is caused by the secretion of pro-inflammatory mediators, such as IL-1α, IL-1β, IL-6, and TNF-α, due to an increase in microglia and astrocytes in Alzheimer’s disease." (PMID 35453602, 2022). "It was revealed that prolonged activation of microglia cells and the resulting overproduction of inflammatory factors, including IL-6, IL-1β, and TNF-α, were significant contributions to the development of Alzheimer's disease." (PMID 36147643, 2022). "In different clinical research, some proinflammatory factors (such as IL-6, IL-1β, and TNF-α) were reported to be overexpressed in patients with Alzheimer's disease and elderly people with mild cognitive impairment." (PMID 36147643, 2022). "Elevated serum IL-6 and CD40L have been reported in many neurological diseases, including multiple sclerosis, Alzheimer’s disease, Parkinson’s disease, and neuromyelitis optica spectrum disorder." (PMID 35264944, 2022). "Chronic neuroinflammation is one of the main drivers of Alzheimer’s disease, and JQ1 treatment has reduced the expression levels of the pro-inflammatory modulators IL-6, IL-1β, and TNF-α, suggesting promise in the treatment of neurological disorders." (PMID 35154163, 2022). "Uro B intervention was found to reduce levels of IL-1β, IL-6 and TNF-α in brains of a mouse model of D-gal-induced Alzheimer disease (AD)." (PMID 35814202, 2022). "Several cytokines (IL-1β, IL-6, TNF-α, IL-8 and IL-15) were further raised in Alzheimer’s disease with systemic infection." (PMID 33723589, 2021). "A recent study stated that donepezil incorporated into PLGA in the presence of Pluronics F68 caused a significant dose-dependent decrease in both gene and protein expression levels of IL-1β, IL-6, GM-CSF and TNF-α in Alzheimer’s disease." (PMID 34502328, 2021). "RES-loaded bilosomes were able to decrease the oxidative stress biomarkers (IL-6 and COX2) and proteins (Tau and ß-amyloid levels that play an important role in Alzheimer disease." (PMID 34683928, 2021). "Another study showed that calycosin treatment decreased the levels of TNF‐α, interleukin (IL)‐6, IL‐1β, and MDA in acute pancreatitis (AP) mice and Alzheimer's Disease mouse." (PMID 32910538, 2020). "Levels of the proinflammatory cytokines IL-6, IL-1β, and TNF-α were significantly increased in AD mice compared with WT mice, confirming that inflammation is an important characteristic of Alzheimer’s disease." (PMID 28106117, 2017).
Alzheimer disease (continued). "We have measured plasma progranulin and interleukin-6 in 230 patients with frontotemporal lobar degeneration (FTLD), 104 patients with Alzheimer's disease, and 161 control subjects." (PMID 25435337, 2015). "JWH133 reduced expression of active p38 MAPK, JNK, and proinflammatory cytokines (IL-1β, IL-6, and TNF-α) induced cognitive improvement in a genetic mice model of Alzheimer's disease." (PMID 24963491, 2014). "Additionally, in the context of Alzheimer’s disease (AD) neuroinflammation, lncRNA MALAT1 downregulates the expression of IL-6 and TNF-α while concurrently enhancing IL-10 levels, suggesting the potential therapeutic value of targeting lncRNA MALAT1 in AD." (PMID 39827195, 2025). "Experimental studies have shown that diabetic patients release pro-inflammatory cytokines such as IL-1β, IL-6, and TNF-α, which may lead to neuronal death and accelerate neurodegenerative changes in Alzheimer’s disease (AD)." (PMID 39157774, 2024). "Sterubin, a flavonoid compound, has been identified as a neuroprotective agent capable of reducing the expression of inflammatory biomarkers (such as IL-6, IL-β, and TNF-α) as well as oxidative stress markers (such as SOD and MDA) in order to prevent chemically-induced Alzheimer’s disease in rats." (PMID 37801482, 2023). "Also, Que can partially block the effect of other genes that play an important role in Alzheimer’s disease, such as tumor necrosis factor-alfa (TNF-α), interleukin 1 beta (IL-1β), and interleukin 6 (IL-6)." (PMID 37507955, 2023). "The binding of these six components to inflammatory mediators (IL-6, TNF-α, IL-1β) and Alzheimer’s disease-related protein targets was studied by molecular docking technology, and it was found that these six components all have low binding energy and good binding fraction." (PMID 36296486, 2022). "IL-6 is increased in cerebrospinal fluid in ALS, Alzheimer's disease and Parkinson's disease." (PMID 35916061, 2022). "In Alzheimer’s disease cases, IL-15, IL-1β, IL-6, TNF-α, and IL-8 were higher in those with than without infection." (PMID 33723589, 2021). "Modelling of acute systemic infection in rodents induces microglial activation and elevated pro-inflammatory cytokine production (IL-1β, IL-6 and TNF-α), and exacerbates cognitive decline, neurodegeneration, and Alzheimer’s disease-like (amyloid-β and tau) pathology in mouse models." (PMID 33723589, 2021). "In this regard, in APP/PS1 transgenic mice, a model of Alzheimer’s disease, chronic treatment with ciproxifan reduced both COX-1 and COX-2 activities, decreased the level of pro-inflammatory cytokines IL-1α, IL-1β, and IL-6, and increased the level of anti-inflammatory cytokine TGF-1β." (PMID 33918940, 2021). "In controls, cortical perfusion declined with increasing IFN-γ, IL-2, IL-4, IL-6, IL-10, IL-12p70, IL-13 and tumour necrosis factor-α (TNF-α) but these relationships were lost with progression of Alzheimer’s disease, and with infection (even in Braak stage 0–II brains)." (PMID 33723589, 2021). "One meta-analysis reported that IL-1β, IL-6, and TGF-β were elevated in PD and the work also revealed the unique inflammatory response profile in the central nervous system of patients with Alzheimer’s disease, PD, and amyotrophic lateral sclerosis." (PMID 32698474, 2020). "Besides the TLR/TNFα/apoptosis/necroptosis pathway as a driver of neurodegeneration in Alzheimer’s disease, we identified a distinct TLR7/IL-6/apoptosis axis in viral neural pathogenesis mediated by TLR7 upon EV71 infection in vivo." (PMID 31730654, 2019). "In contrast, peripheral IL-6 level was not significantly higher in elderly with Alzheimer’s disease as compared to controls." (PMID 30104698, 2018). "While IL-6 and IL-8 have been extensively studied for their role in Alzheimer’s disease and PD, not much is known about the role of these cytokines in HAND." (PMID 25539898, 2014).
Alzheimer disease (continued). "Activation of the TLR pathway increases the expression of various pro-inflammatory cytokines, like IL-6, IL-1 and TNF-α.While earlier evidence has been obtained in the field of Alzheimer’s disease (AD) and Multiple Sclerosis (MS), recent studies have implicated TLRs also in the pathogenesis of PD." (PMID 25099483, 2014). "Downstream targets of IL-6, mainly JAK/STAT, regulate neuroinflammation and affect the survival of neuronal and glial cells, as evidenced by the dysregulation of JAK/STAT pathway in brain disorders, such as brain cancers, ischemia, and Alzheimer’s disease (AD)." (PMID 40843259, 2025). "Emerging evidence implicates the IL-6–CRP axis in the amplification of pain perception, central sensitization, and stress hypersensitivity, ultimately promoting neurodegenerative processes such as those observed in Alzheimer’s disease (AD) and vascular dementia." (PMID 41373439, 2025). "For example, IL-6 is a cytokine that may directly contribute to the negative impact of inflammation in Alzheimer’s disease." (PMID 38276010, 2024). "A study on Alzheimer’s disease showed that EA at GV20 and EX-HN3 acupoints could effectively improve the learning and memory of mice and reduce the expression of interleukin-1β (IL-1 β), interleukin-6 (IL6), and tumor necrosis factor-α (TNF-α)." (PMID 37304438, 2023). "However, in a meta-analysis, compared with controls, only IL-1β was significantly elevated in Alzheimer’s disease but not IL-6, TNF-α or CRP and the significance did not survive Bonferroni-correction." (PMID 37467176, 2023). "However, some studies have found that the increase of peripheral blood IL-6 level precedes the onset of Alzheimer’s disease rather than during the onset of Alzheimer’s disease." (PMID 36437994, 2022). "Previous studies illustrated that Th17 cells were found in the vicinity of neuritis plaques in AD brains, along with increased pro-inflammatory cytokines (IL-1β, IL-6, CXCL1, and TNF-α) in peripheral blood, which may contribute to the development of Alzheimer’s disease." (PMID 35669784, 2022). "However, elderly with Alzheimer’s disease only had significantly higher peripheral levels of IL-1β (p = 0.047) but not IL-6 (p = 0.138), TNF-α (p = 0.735) or CRP (p = 0.0712)." (PMID 30104698, 2018). "Levels of interleukin (IL)-6 and tumor necrosis factor (TNF)-α (pg/mL) released by peripheral whole blood cells of adult and elderly healthy subjects, as well as of mild Alzheimer’s disease (mAD) and severe Alzheimer’s disease (AD) patients, after 4 h of culture in basal conditions." (PMID 29375582, 2017). "For example, plasma levels of IL-6, but not TNF-α, increased after a 16-week duration of moderate-to-high-intensity aerobic physical exercise in Alzheimer’s disease patients." (PMID 36156182, 2022). "Except for IL-6 and IL-13, brain cytokine level was not related to possession of APOE ε4 in either controls or Alzheimer’s disease brains (Supplementary)." (PMID 33723589, 2021). "While we included leptin, IL-6, IL-1β, TNF-α, and CRP, we did not assess other cytokines such as MCP-1, IL-18, or markers of microglial activation and phenotype (e.g., CD68 and sTREM2), which may play significant roles in glial reactivity in Alzheimer's disease." (PMID 40521397, 2025).
chronic kidney disease (308 papers, 2010 to 2026). Impairment of the renal function secondary to chronic kidney damage persisting for three or more months. "A recent large two sample Mendelian randomization study found that people with risk alleles associated with greater circulating IL-6 levels, had a 24% increased risk of developing end-stage renal disease (odds ratio 1.24, 95% CI 1.01 to 1.52)." (PMID 40235955, 2025). "Chronic kidney disease amplifies IL-6-driven risk and increases susceptibility to ischemic and bleeding complications." (PMID 41302946, 2025). "Ziltivekimab, a novel monoclonal antibody targeting IL-6 has shown strong anti-inflammatory effects in patients with chronic kidney disease and high cardiovascular risk by significantly lowering hsCRP and other inflammatory markers." (PMID 41511355, 2025). "Another study showed that markers of inflammation (including high-sensitivity C-reactive protein, tumor necrosis factor- α receptor 2, white blood cell count, and interleukin-6) predict the long-term risk of developing chronic kidney disease." (PMID 39677959, 2024). "Specifically, several markers of inflammation, including interleukin-6 (IL-6) and tumor necrosis factor-α (TNFα), have been particularly implicated in the progression of chronic kidney disease." (PMID 37033595, 2023). "CSF1 and IL6 were previously found to be associated with kidney function and chronic kidney disease (CKD)." (PMID 37691946, 2023). "Systemic inflammation, measured as circulating Interleukin-6 (IL-6) levels, is associated with cardiovascular and all-cause mortality in chronic kidney disease." (PMID 37884903, 2023). "The study found that neutrophils in patients with chronic renal failure were significantly higher than those in healthy people, and were associated with IL-6 and TNF-α." (PMID 38152332, 2023). "Chrysin ameliorates adenine-induced chronic kidney disease, which causes inflammation by increasing the plasma concentration of IL-1β and IL-6." (PMID 36552226, 2022). "In a chronic renal insufficiency cohort study, inflammation markers (IL-1β, IL-1 receptor antagonist, IL-6, TNF-α, hs-CRP, and fibrinogen) were associated with decreased kidney function." (PMID 35628912, 2022). "Contrary to our results, only one longitudinal study in hypertensive patients with chronic kidney disease showed that higher IL-6 at baseline was associated with increased LVMI after 3 years of follow-up." (PMID 33945586, 2021). "High levels of diverse pro-inflammatory cytokines such as interleukin-6 (IL-6) expression levels were observed consistently in the kidneys collected from chronic kidney disease animal models and human associated hypertensive studies." (PMID 29461477, 2018). "Among many inflammatory mediators IL-6 is a predictor of mortality in chronic kidney disease, in HIV, and in other chronic diseases associated with immune activation due to microbial translocation." (PMID 25762501, 2014). "Hemodialysis (HD) and hemodiafiltration clear only with a low efficiency the plasma from interleukin-6 and p-cresol, two protein-bound uremic toxins associated with high cardiovascular risk in end stage renal disease." (PMID 24755610, 2014). "Elevated levels of interleukin-6 and tumor necrosis factor-alpha in the circulation are associated with vascular calcification in patients with chronic kidney disease." (PMID 23199021, 2012). "Elevated levels of pro-inflammatory cytokines, such as interleukin-6 and tumor necrosis factor-alpha, have been consistently implicated in the pathogenesis and progression of chronic kidney disease, contributing to renal inflammation, fibrosis, and accelerated decline in glomerular filtration rate." (PMID 41602165, 2026). "IL-6 polymorphisms can elevate the risk of AS, and IL-6 may mediate pro-inflammatory AS in patients suffering from chronic kidney disease (CKD)." (PMID 40777986, 2025).